SOX2 (SRY-box transcription factor 2)
Diseases named in the same sentence as SOX2 in open-access papers (continued):
Sharing a sentence is not in itself a finding about the gene and the disease.
oral cancer (23 papers, 2012 to 2026). "It is worth noting that several of the functional partners including CTNNB1, SHH, FOXA2, and SOX2 have been reported to be involved in the progression of oral cancer or linked with the stem cell phenotype of oral cancer cells." (PMID 38304730, 2024). "In conclusion, SOX2 expression emerges as an independent predictor of oral cancer risk in patients with oral leukoplakia." (PMID 31640140, 2019). "Univariate Kaplan–Meier and Cox analysis showed that the SOX2 expression and histological grading were significantly associated with oral cancer risk." (PMID 31640140, 2019). "Univariate analysis showed that SOX2 expression and histopathological grading were significantly associated with oral cancer risk; and both were found to be significant independent predictors in the multivariate analysis." (PMID 31640140, 2019). "Together, our results reveal that SOX2 expression is a clinically relevant feature in early stages of oral tumorigenesis, and provide original evidence of its potential utility as biomarker for oral cancer risk assessment." (PMID 31640140, 2019). "Furthermore, dysplasia grading and SOX2 expression were both found to be significant independent predictors of oral cancer risk in multivariate analysis." (PMID 31640140, 2019). "In addition, positive SOX2 expression also significantly predicted oral cancer risk either considering SOX2 > 10 (log-rank test, P = 0.02) or SOX2any (log-rank test, P = 0.01) as cut-off points." (PMID 31640140, 2019). "Deaths attributed specifically to oral cancer were observed in 70% of the low SOX2 group, whereas this was lower at 51% in the high SOX2 group." (PMID 40227667, 2025). "In relation to prDFS, 43% of the patients showing low SOX2 expression died from oral cancer, in contrast to 34% in the high SOX2 cohort." (PMID 40227667, 2025). "A recent retrospective study also highlights that SOX2 is overexpressed in pre-malignant oral disorders and that this predicts for oral cancer evolution." (PMID 38096163, 2023). "For example, oral cancer cells overexpressing the core pluripotency factors SOX2 and POU5F1/OCT4 in xenograft mouse model assays were thought to represent reprogrammed cells capable of inducing tumorigenesis." (PMID 37761874, 2023). "In the present study, we examined its impact on the cancer stemness traits of oral cancer CSCs in vitro and in vivo, and showed that butylidenephthalide inhibited the expression of Sox2 and Snail in the ALDH1+/CD44+ cells." (PMID 35682836, 2022). "It is important to note that other studies point towards an anti-oncogenic effect of miR-146a-5p related to the targeting of SOX2 in oral cancer cell lines." (PMID 34439138, 2021). "Here, we identified that gefitinib decreases the expression of SOX2, a critical cancer stem cell regulator, and attenuates the oncosphere formation activity of oral cancer cells." (PMID 31823521, 2020). "It has been demonstrated that SOX2 in oral cancer has two cytoplasmic staining patterns known as disseminated and peripheral." (PMID 31244283, 2019). "The effect of forced expression of BRACHYURY or/and SOX2 on cell migration of oral cancer cells in vitro was analysed using a wound healing assay." (PMID 30453543, 2018). "In this study, we used forced expression of BRACHYURY and SOX2 in oral cancer cell lines to confirm that BRACHYURY and SOX2 are regulators of the CSC phenotype." (PMID 30453543, 2018). "Results from another group suggested that the silencing of Sox2 suppressed drug-resistance and anti-apoptotic genes, and they observed that the expression level of Snail, Slug, Twist, and vimentin were repressed in the CSCs of oral cancer." (PMID 35682836, 2022). "This new knowledge is expected to lead to more specific and effective therapeutic targets in oral cancer, which may include SOX2 and BRACHYURY, either alone or in combination." (PMID 30453543, 2018). "We found that BRACHYURY and SOX2 synergistically promote cancer stemness in oral cancer cells." (PMID 30453543, 2018).
oral cancer (continued). "BRACHYURY, SOX2, or both were stably transfected into oral carcinoma cell lines." (PMID 30453543, 2018). "SOX2 knockdown effectively inhibits the antiapoptotic gene expression and drug resistance and enhances the DDP sensitivity of oral cancer cells." (PMID 36247876, 2022). "On the other hand, it was demonstrated that the gene expression of Sox2 was upregulated in the Snail-overexpressing oral cancer cells, but the changes at the protein level were not significant (only Nanog, Bmi1, and ABCG2 were increased)." (PMID 35682836, 2022). "They suggested that the expression of SOX2 is a suitable indicator of the absence of regional lymph nodes metastasis in oral cancer." (PMID 31244283, 2019). "Low QKI expression was detected in oral cancer tissues and oral cancer stem cells, but cell and mouse experiments indicated that QKI could inhibit cancer stem cell sphere formation by binding to and inhibiting the 3' untranslated region of SOX2." (PMID 32931453, 2020). "Accordingly, it has been proposed that, in the absence of SOX2 expression, CSC self-renewal that sustains tumor growth could be abrogated,; therefore, supporting SOX2 inhibition as a potentially relevant therapeutic target for oral cancer." (PMID 31640140, 2019).
Stroke (22 papers, 2013 to 2025). Sudden impairment of blood flow to a part of the brain due to occlusion or rupture of an artery to the brain. "We found that stroke surgery led to a significantly higher count of BrdU+/SOX2+ cells on the ipsilateral side when compare with the Sham group (p < 0.001)." (PMID 39697542, 2024). "In young mice, stroke increased the number of Ki67+ proliferative cells and tdTomato+Sox2+ precursors in the SVZ relative to young naïve, aged naïve, and aged stroke mice." (PMID 37816732, 2023). "In this study, As IV promoted the expression of the DCX, BrdU, and Sox2 proteins in the subgranular zone (SGZ) after stroke in vivo." (PMID 32317974, 2020). "In this study, knocking out IL-17 significantly promoted the expression of BrdU, DCX, Nestin, and Sox2 in the SGZ after stroke in vivo, which was consistent with the results by giving As IV above." (PMID 32317974, 2020). "After 7 days of stroke, SOX2-positive cells and BrdU/DCX-double positive proliferative NPCs were significantly increased at the ipsilesional SVZ of the WT-Vehicle mice in line with the findings of previous studies." (PMID 31606043, 2019). "In vivo enforcement of transcriptional factors (Ascl1, Sox2 and NeuroD1) successfully induced ectopic neuronal cells in the ipsilateral cerebral cortex and lateral striatum of the post-stroke mice brain." (PMID 31358888, 2019). "Taken together, the present study successfully achieved, for the first time, in vivo direct reprogramming by enforced transcriptional factors (Ascl1, Sox2 and NeuroD1) in the post-stroke mouse brain." (PMID 31358888, 2019). "The stem/progenitor cell expression pattern at 6 weeks after stroke was evaluated by the number of Sox2 positive human cells in the stroke area and showed a significantly reduced number in the HA Min condition compared with the HA group." (PMID 27995155, 2017). "In contrast, only a small number of BrdU+ cells at 8 weeks post-stroke were Sox2-positive, indicating relatively scant production of new, long-lived neural stem cells and astrocytes." (PMID 27803646, 2016). "At 8 weeks post-stroke, only a small percentage (approximately 2–5%) of BrdU+ cells in each group was positive for Sox2, which labels neural stem cells, early intermediate progenitors, and mature astrocytes in the adult rat brain." (PMID 27803646, 2016). "Moreover, it notably amplified neurogenic responses post-stroke, evidenced by the proliferation of BrdU/SOX2 and BrdU/DCX in the subventricular zone, and their subsequent differentiation into BrdU/NeuN and BrdU/VgulT1 in the ischemic penumbra." (PMID 39697542, 2024). "We further characterized the in vivo profile of surviving drNPCs (HuNu+ or STEM121+ cells) at 32 days post-stroke using immunostaining for Sox2 and Nestin (undifferentiated NPCs), GFAP (astrocytes), TUJ1 (immature neurons), NeuN (mature neurons), and Olig2 (oligodendrocytes)." (PMID 30747366, 2020). "We view the significant increase of BrdU+Sox2+ positive cells in the ipsilateral side SVZ in GET-1 mice when compared with those of Ntg mice at 7 days after stroke suggested that ET-1 overexpression also promoted ischemia-induced NSC proliferation (**p < 0.01)." (PMID 31733648, 2019). "Our study is the first to reveal that miR-132 may regulate the expression of SOX2, which provides a new mechanism of EA treatment after stroke." (PMID 30618618, 2018). "Additionally, aLA increased the relative mRNA expression of SOX2 and nestin when compared with the control group at 3 days after stroke (P < 0.05)." (PMID 25761600, 2015). "We found that 28% of NG2-tdT+ cells were Sox2+ i-NSCs at the site of stroke injury at 3 days post-injury (dpi), while only 10% of NG2-tdT+ cells were Sox2+ i-NSCs at 1 dpi." (PMID 39431007, 2024). "Brain sections were co-stained for BrdU/SOX2 (the recognized phenotypic marker for NSCs) and BrdU/DCX (the neuroblast marker) in the SVZ at 35 days after stroke to identify the proliferating and migrating cells, respectively." (PMID 39697542, 2024).
Stroke (continued). "In the present study, to observe the neurogenesis in ischemic cortex after stroke regulated by IL-17 and As-IV, NPC markers-Nestin, GFAP and Sox2 and immature neuron marker-DCX, and mature neuron marker-NeuN protein expression was chose." (PMID 32818074, 2020). "In contrast with the reactive neurogenesis that has been shown to occur in the primate sensorimotor system after injury and in the caudate nucleus and cortex after stroke, here we found that MPTP markedly decreased the percentage of Sox-2+/CR+ cells in the striatum." (PMID 23824751, 2013).
pancreatic ductal adenocarcinoma (18 papers, 2013 to 2025). An infiltrating adenocarcinoma that arises from the epithelial cells of the pancreas. "NR5A2 is mainly expressed in the pancreas and liver, making it an attractive target for selectively inhibiting SOX2 in pancreatic ductal adenocarcinoma (PDAC)." (PMID 38012687, 2023). "Exosomal SOX2OT promotes EMT and stem cell-like properties by regulating SOX2 expression in pancreatic ductal adenocarcinoma." (PMID 32019566, 2020). "SOX2OT (SOX2 overlapping transcript) lncRNA enriched in exosomes from pancreatic ductal adenocarcinoma cells, promotes EMT and stem cell-like properties by regulating SOX2 (SRY-box 2) expression, thus inducing cancer invasion and metastasis." (PMID 31752198, 2019). "Given that more than 90% of clinical specimens of pancreatic duct adenocarcinoma possess mutant K-ras, the effect of SOX2 downregulation by 6-MITC and I7557 in PANC-1 cells may have potential for further preclinical investigation." (PMID 24575144, 2014). "Positive regulation of SOX2 gene expression by LncRNA SOX2‐OT could also be the result of sponging activity targeting miR‐200c (miR200 subfamily members), which has been detected in pancreatic ductal carcinomas." (PMID 33433063, 2021). "In pancreatic ductal adenocarcinoma, OGT promotes tumor recurrence by modifying and stabilizing the transcription factor SOX2, while OSMI treatment markedly reduces the O‐GlcNAcylation level and stability of SOX2, thus decreasing recurrence." (PMID 41394960, 2025). "Furthermore, both inducible overexpression and inducible knockdown of SOX2 in pancreatic ductal adenocarcinoma (PDAC) cells lead to a significant reduction in tumor growth, indicating that SOX2 levels in these cells are optimized to maximize tumor growth." (PMID 32998722, 2020).
laryngeal carcinoma (17 papers, 2014 to 2026). Carcinoma that arises from the laryngeal epithelium. "Concerning the head and neck region, the expression of SOX2 was found much higher in laryngeal carcinoma tissues, and high SOX2 expression is associated with late clinical stage and early recurrence in laryngeal carcinoma." (PMID 41463190, 2025). "The combination of PIK3CA and SOX2 amplification also significantly predicted the laryngeal cancer risk (Log-rank test p = 0.033)." (PMID 38473941, 2024). "The PIK3CA and SOX2 amplifications were predominant in high-grade dysplasias and significantly associated with laryngeal cancer risk beyond histological criteria." (PMID 38473941, 2024). "In marked contrast, we found that SOX2 gene amplification significantly correlated with an increased laryngeal cancer risk (log-rank p = 0.038)." (PMID 30823625, 2019). "Our findings also uncover the clinical application of SOX2 expression as an independent predictor of laryngeal cancer risk in patients with precancerous lesions beyond current WHO histological grading." (PMID 30823625, 2019). "Univariate Cox analysis showed that SOX2 gene amplification (p = 0.046) and protein expression (p < 0.001) but not histological grading (p = 0.432) were significantly associated with laryngeal cancer risk." (PMID 30823625, 2019). "Our findings uncover the clinical application of SOX2 expression as an independent predictor of laryngeal cancer risk in patients with laryngeal precancerous lesions, showing superior predictive value to the current World Health Organization (WHO) histological classification." (PMID 30823625, 2019). "Furthermore, SOX2 protein expression showed the most robust association with laryngeal cancer risk (log-rank p < 0.001)." (PMID 30823625, 2019). "Furthermore, this study uncovers SOX2 expression as a robust independent predictor of laryngeal cancer risk beyond histological evaluation." (PMID 30823625, 2019). "Even though SOX2 protein expression and SOX2 amplification were found to increase in high-grade dysplasias, SOX2 protein expression and gene amplification but not histological grading were significantly associated with progression to laryngeal cancer." (PMID 30823625, 2019). "Sox2 plays an important role in the early stage of tumorigenesis in laryngeal cancer tissues when compared to normal laryngeal tissues." (PMID 39452555, 2024). "Sox2, a transcription factor crucial in preserving stem cell characteristics, has been connected to the laryngeal carcinoma CSC phenotype." (PMID 39452555, 2024). "In laryngeal cancer, SOX2 promotes migration and invasion by inducing MMP-2 via the PI3K/Akt/mTOR pathway." (PMID 33344262, 2020). "Specifically, higher SOX2 expression was reported to have better prognosis in oral cavity cancer, and the opposite result was reported in laryngeal cancer." (PMID 33182283, 2020). "In multivariate stepwise analysis including age, tobacco, histology, SOX2 gene amplification, and SOX2 expression, SOX2 expression (HR = 3.531, 95% CI 1.144 to 10.904; p = 0.028) was the only significant independent predictor of laryngeal cancer development." (PMID 30823625, 2019). "All these results are consistent with the existing studies that silencing SOX2 expression by RNA interference can inhibit the proliferation, invasion and metastasis, and induces apoptosis in human laryngeal cancer." (PMID 30186173, 2018). "miR-27 asignificantly rescued differentiation and inhibited β-catenin, LEF1, OCT4 and SOX2 in Wnt/β-catenin pathway in all-trans-retinoic acid (ATRA)-induced laryngeal cancer cells." (PMID 28122350, 2017). "Subsequent in vitro studies with breast, prostate and laryngeal cancer cells also showed that SOX2 over expression promoted EMT." (PMID 26370982, 2015). "Additionally, studies have demonstrated that SOX2 contributes to the progression of laryngeal cancer, where it exerts crucial regulatory effects on apoptosis and metastasis of laryngeal cancer cells through the MAP4K4/JNK signaling pathway." (PMID 39976818, 2025).
laryngeal carcinoma (continued). "Furthermore, combined amplification of both the PIK3CA and SOX2 genes was found the strongest predictor of laryngeal cancer by ROC curve analysis (AUC = 0.675, p = 0.021)." (PMID 38473941, 2024). "Previous reports have shown that C-myc, Oct-4, Nanog and Sox-2, as biomarkers of CSCs, have not been reported to be associated with laryngeal cancer." (PMID 38095348, 2023). "SOX2 was found during early tumorigenesis of laryngeal cancer and its expression could be used as independent predictor of laryngeal cancer risk in patients with precancerous lesions." (PMID 33344262, 2020). "Our findings demonstrate that SOX2 protein expression and gene amplification are frequent events in laryngeal tumorigenesis and, more importantly, both emerge as clinically and biologically relevant features in laryngeal cancer development." (PMID 30823625, 2019). "Univariate Cox analysis showed that SOX2 gene amplification and protein expression but not histological grading were significantly associated with laryngeal cancer risk." (PMID 30823625, 2019). "It plays an oncogenic role enhancing laryngeal cancer cell migration, tumor sphere formation, and tumor growth by regulating CARM1/Sox-2 axis." (PMID 35406495, 2022). "Five years after the patients were diagnosed, 20 (53%) of the 38 patients with SOX2-positive expression developed laryngeal cancer, whereas only 9 (16%) of the 56 patients with SOX2-negative expression progressed to invasive carcinoma (p < 0.001)." (PMID 30823625, 2019).